HRH1 (histamine receptor H1)
Diseases named in the same sentence as HRH1 in open-access papers (continued):
Sharing a sentence is not in itself a finding about the gene and the disease.
ovarian tumor (1 paper, 2022). "Histamine activates the histamine receptor H1 (HRH1), which stimulates the growth of ovarian tumor cells in vitro and promotes the release of extracellular vesicles (EVs) that modulate different steps of the metastatic process." (PMID 35625966, 2022).
psychotic disorder (1 paper, 2024). An abnormal condition of the mind that involves a loss of contact with reality. "A previous study has demonstrated a significant association between the Hrh1 gene variants rs346070 and rs346074 and B.M.I. in Caucasian patients with a psychotic disorder." (PMID 38931172, 2024).
somnolence (1 paper, 2018). "Additionally, a correlation was revealed between clozapine-induced somnolence and rs2737385 polymorphism on HNMT gene, rs1552498 and rs17034063 polymorphisms on HRH1 gene (Histamine Receptor H1), as well as rs697738 polymorphism on AOC1 gene (Amine Oxidase Copper Containing 1)." (PMID 29587340, 2018).
stress-related disorder (1 paper, 2025). Stress-related disorders are mental health disorders that are a result of an atypical response to both short and long-term anxiety due to physical, mental, or emotional stress. "Notably, SCOPE uncovered a novel role for the histamine receptor HRH1, which was validated by RNAi knockdown and pharmacological inhibition, implicating HRH1 as a potential therapeutic target in ER stress-related disorders." (PMID 40791405, 2025).
trauma (1 paper, 2021). "The genes that were found to downregulate the most during a fight were ADRB2, HRH1, ANXA1 and PDE4B, with the first two upregulated at baseline for pre-fight samples when compared to control data and the latter two with pre-fight gene expression similar to non-head trauma controls." (PMID 33854105, 2021).
tuberculosis (1 paper, 2022). A chronic, recurrent infection caused by the bacterium Mycobacterium tuberculosis. "In conclusion, we described the interaction between HRH1 and M. tuberculosis and clarified the underlying mechanism, which broadens our understanding of M. tuberculosis-host interaction and may provide useful information for the development of novel anti-TB strategies in the future." (PMID 36000734, 2022).
cancer (36 papers, 2012 to 2026). A tumor composed of atypical neoplastic, often pleomorphic cells that invade other tissues. "Of the 40 common drugs taken among cancer patients, only HRH1 blockers were significantly associated with improved patient survival (P=0.005), and this association was only demonstrated in patients taking immunotherapy." (PMID 38299150, 2023). "Cationic amphiphilic drugs targeting HRH1 are currently under investigation for repurposing into cancer therapy." (PMID 41603740, 2026). "Analysis of different cancer cohorts from TCGA revealed elevated HRH1 levels across various cancer types, with a particularly significant increase observed in HNSCC." (PMID 40113769, 2025). "Both the histamine-dependent and—independent roles of HRH1 in cancer progression were also observed in HCC." (PMID 40113769, 2025). "In this context, azelastine, a second-generation HRH1 antagonist widely used as an anti-allergy drug, has also been reported to exert anti-proliferative actions in various cancer cells." (PMID 41465279, 2025). "Results indicated that HRH1 exhibited prognostic potential for unfavorable outcomes in various human cancers, including LUAD." (PMID 39886963, 2025). "To further validate the expression of HRH1, we measured the protein levels in cancer cell lines via western blotting." (PMID 38715057, 2024). "HRH1 expression in cancer cells was negatively correlated with HLA-ABC expression, CD8+ T cells, and cytotoxic CD8+ T cells." (PMID 38715057, 2024). "Although HRH1 has been targeted in cancer therapy with favorable outcomes, only a few studies have delved into its relationship with the immune system." (PMID 38715057, 2024). "In summary, HRH1 inhibition significantly impacts MHC-I expression in cancer cells, potentially altering the “cold” to “hot” immunogenic status in PDAC." (PMID 38715057, 2024). "In our in vitro experiment, co-culture with CAFs led to significantly reduced MHC-I expression in cancer cells, a decrease reversed by HRH1-antagonist-pretreated CAFs, suggesting that CAFs diminish MHC-I expression." (PMID 38715057, 2024). "We found that single-cell RNA sequence data derived from patients with PDAC showed the expression level of HRH1 in cancer cells is negatively correlated with the expression level of CD3D+, CD8A+ T cells." (PMID 38715057, 2024). "The roles of histamine and histamine receptor H1 (HRH1) in cancer pathogenesis remain controversial." (PMID 36732336, 2023). "It was also found the HRH1 activation increased T cell dysfunction in 9 of 12 cancer types evaluated." (PMID 38299150, 2023). "Histamine and its receptor, HRH1, are known to play important roles in many aspects of cancer development including cell proliferation." (PMID 35587368, 2022). "Meanwhile, the authors transplanted WT or HRH1−/− macrophages with various types of cancer cells into recipient mice, and finally determined that activation of HRH1 in macrophages inhibited CD8+ T cell response and promoted tumor growth." (PMID 35378699, 2022). "A pan-cancer analysis indicated that HRH1 expression is altered in numerous malignancies." (PMID 41465279, 2025). "In addition to HRH1 overexpression, histamine, an HRH1 agonist, was reported to be elevated in various cancer types and to act as an autocrine growth factor in promoting cancer progression." (PMID 40113769, 2025). "Additionally, HRH1-KD also remarkably reduced migration and invasion, two key elements of cancer metastasis, in both OSCC cell lines." (PMID 40113769, 2025). "Mouse cancer cells expressed various levels of HRH1 protein." (PMID 38715057, 2024). "Next, we orthotopically transplanted CAF1 and HRH1 knockdown cancer cells into C57BL/6N mice." (PMID 38715057, 2024). "Our results suggest that the systemic pharmacological blockade of HRH1 may play a multifunctional role in enhancing antigen presentation in cancer cells." (PMID 38715057, 2024). "We examined mRNA expression levels of HRH1 in KPC-derived cancer cell lines." (PMID 38715057, 2024).
cancer (continued). "However, compared to the other HRH family members, the impacts of HRH1 SNPs in cancers have been less well investigated." (PMID 35587368, 2022). "However, various mechanisms of histamine and HRH1 in cancer development have remained largely elusive to date." (PMID 35378699, 2022). "HRH1 had different prognostic implications in various cancer types." (PMID 35804895, 2022). "HRH1 is also known to function in normal and cancer breast cell lines and tissue." (PMID 34378323, 2021). "Therefore, we investigated whether genetic deletion of HRH1 in cancer cells can enhance the therapeutic efficacy of αPD-1 treatment." (PMID 38715057, 2024). "Our data also suggest that HRH1 might be important for cancer progression." (PMID 26673618, 2016). "Further examination of the influence of cancer heterogeneity, such as "basal-like" type and "classical" type PDAC, showed high levels of HRH1 mRNA expression in both types." (PMID 38715057, 2024). "Combined use of an HRH1 antagonist and anti-PD-1 antibody notably suppressed PDAC growth in mouse models, indicating the potential to improve prognosis in this cancer type." (PMID 38715057, 2024). "Costimulation of CXCR4 and HRH1 synergistically increases calcium flux and CXCL12-induced cell migration in various cancer cells that express CXCR4 and HRH1 endogenously." (PMID 36732336, 2023). "Li and colleagues recently demonstrated in Cancer Cell that the histamine receptor H1 (HRH1) axis could serve both as therapeutic targets for enhancing immunotherapy response and predictive biomarker of T cell exhaustion and therapeutic effectiveness in cancer immunotherapy." (PMID 35378699, 2022). "Our analysis of HRH1, NRP2, and STX1A expression using the GOBO database corroborated the overexpression of HRH1 and NRP2 in basal-like and HER2-enriched cancer subtypes, while STX1A was overexpressed only in HER2-enriched and luminal B subtypes." (PMID 26673618, 2016). "Techniques including Western blot, flow cytometry, quantitative reverse transcription polymerase chain reaction (RT-PCR), and microarray analyses were performed to identify the relationships between HRH1 and major histocompatibility complex class I (MHC-I) expression in cancer cells." (PMID 38715057, 2024). "HRH1 transcript levels were higher in cancer tissues than in normal or adjacent non-tumor tissues." (PMID 38715057, 2024). "It was found that the HRH1 blocker, desloratadine demonstrated the greatest reduction in hazard ratio of all HRH1 blockers compared to cancer patients who took no supplemental drugs in addition to their cancer therapy." (PMID 38299150, 2023). "The Hrh1 antagonist failed to induce apoptosis of cancer cells." (PMID 26907350, 2016). "In addition, analyzing data from The Cancer Genome Atlas, the expression profiles of HRH1 and TSC2 were found to be negatively correlated (PCC = −0.15, P = 2 × 10‐6) and, conversely, HRH1 expression was found to be positively correlated with the canonical lung‐metastasis signature and mTOR pathway." (PMID 34378323, 2021). "However, the Hrh1 antagonist did not affect the proliferation activity of cancer cells." (PMID 26907350, 2016). "A decrease in expression regardless of cancer grade was observed for CALM2, DRD5, ICAM1, while EGR1, HRH1, HRH2, HRH3 were overexpressed." (PMID 34768392, 2021).
tumor (32 papers, 2016 to 2026). "Regarding the roles of HRH1 and STAT3 in immune escape, HRH1 was reported to shift macrophages toward an M2-like tumor-associated macrophage (TAM) phenotype, with increased expression of the VISTA immune checkpoint, rendering CD8+ T cells dysfunctional." (PMID 40113769, 2025). "Results indicated that HRH1 expression hazard ratio (HR), 1.369; p = 0.024), LN metastasis (HR, 1.861; p < 0.001), and tumor size (HR, 1.983; p < 0.001) were all associated with adverse impacts on OS." (PMID 40113769, 2025). "In particular, HRH1 was most strongly associated with immunosuppressed M2-like macrophages among a variety of cell types of human tumor microenvironment." (PMID 35378699, 2022). "Further analysis in tumor-derived cell lines showed that HRH1 expression was positively correlated with tumor-associated macrophages (TAMs)." (PMID 35378699, 2022). "Recent translational research suggests that upregulation of both histamine and the histamine receptor H1 (HRH1) in the immunosuppressive tumor microenvironment (TME) occurs with the polarization of tumor‐associated macrophages (TAMs) toward the M1‐like phenotype by HRH1 activation." (PMID 39791941, 2025). "In addition, tumor growth inhibition was observed in T cell deficient mice treated with HRH1 antagonists, marked by decreased αSMA and Sirius red expression, indicating decreased levels of CAF activation." (PMID 38715057, 2024). "Collectively this data suggests that H1 blockade might be most efficacious in those patients with “high” level expression of HRH1 on tumor associated macrophages and high (approximately > 0.6 ng/ml) histamine blood levels." (PMID 38299150, 2023). "HRH1 genotypes at four loci (rs346074, rs346076, rs901865, and rs2606731) were analyzed by a TaqMan allelic discrimination assay, and we found that patients harboring HRH1 rs901865 T and rs346074 T alleles had a significantly lower risk of developing larger tumor sizes (>T2) under a dominant model." (PMID 35587368, 2022). "Histamine receptor H1 (HRH1) is upregulated within the tumor microenvironment, where it supports tumorigenesis by several mechanisms." (PMID 41603740, 2026). "Double KD of HRH1 and STAT3 in HSC-3M cells exhibited the strongest inhibitory effect on tumor growth compared to either HRH1-KD or STAT3-KD alone." (PMID 40113769, 2025). "Upon sacrifice of the mice at the end of the experiment (21 days post-cell injection), visible tumor masses were smaller in the HRH1-KD group than in the control group." (PMID 40113769, 2025). "Results of the IHC analysis revealed upregulation of STAT3 phosphorylation in tumor tissues in which HRH1 was knocked down." (PMID 40113769, 2025). "In vivo photon emission detection revealed that HRH1-KD led to attenuated tumor growth compared to the control group." (PMID 40113769, 2025). "Combining inhibition of HRH1 and STAT3 using their respective inhibitors or short hairpin (sh)RNAs enhanced the tumor-suppressive effects compared to HRH1 inhibition/depletion alone in OSCC cells and a xenograft model." (PMID 40113769, 2025). "It has been reported that histamine and its receptor HRH1, often upregulated in the tumor microenvironment, can induce T cell dysfunction." (PMID 38388661, 2024). "This study demonstrated that anti-PD1 treatment combined with pharmacological or genetic HRH1 inhibition significantly enhanced tumor growth suppression in PDAC mouse models." (PMID 38715057, 2024). "For instance, the interaction between tumor-derived histamine and macrophage histamine receptor H1 (HRH1) can lead to T cell dysfunction." (PMID 38978014, 2024). "Histamine receptors, particularly HRH1 and HRH2, have been implicated in tumor growth, angiogenesis, invasion, and metastasis." (PMID 39267843, 2024). "Low numbers of CD8+ T cells were observed in the tumor, while histamine and HRH1 were upregulated in the tumor microenvironment (TME)." (PMID 38299150, 2023).
tumor (continued). "In short, allergy promoted tumor growth and induced immunotherapy resistance through the histamine-HRH1 axis." (PMID 35378699, 2022). "Of note, M2 macrophages are similar in phenotype to TAMs, promoting tumor growth and metastasis, while blocking HRH1 reduced M2-like macrophages cell composition." (PMID 35378699, 2022). "HRH1, an NSCLC survival hazard gene found in this study, was underexpressed in NSCLC tumor B cells and was associated with resistance to erlotinib and vinorelbine in human NSCLC epithelial cell lines." (PMID 35804895, 2022). "Altogether, these data indicated that blocking the binding of tumor-derived or allergy-released histamine to HRH1 on TAMs enhanced cytotoxic T cell function and alleviated immunosuppression of TME." (PMID 35378699, 2022). "Here, wild-type (WT) and HRH1 knockout (HRH1−/−) bone marrow derived macrophages were isolated and cultured in tumor-cell-conditioned medium (TCM)." (PMID 35378699, 2022). "Analogous in vivo assays confirmed significant tumor growth reduction when the cells were depleted in Maoa or Hrh1 expression and in mice treated with rapamycin, relative to pLKO‐transduction and equivalent administration of rapamycin." (PMID 34378323, 2021). "Depletion of Maoa and Hrh1 expression with short‐hairpin RNA sequences (shRNAs) also revealed tumor growth inhibition, relative to shRNA control pLKO." (PMID 34378323, 2021). "Furthermore, compared to normal tissue, HRH1 expression was significantly lower across all tumor stages (Stage I-IV) (Kruskal–Wallis p = 2.85 × 10−8)." (PMID 41465279, 2025). "Higher HRH1 levels also showed a trend toward larger tumor sizes." (PMID 40113769, 2025). "Additionally, analysis of two HRH1 probes (205579_at and 205580_at) in an OSCC cohort from the GSE78060 dataset demonstrated higher HRH1 levels in tumor tissues compared to normal tissues." (PMID 40113769, 2025). "Additionally, HRH1, which correlated negatively with cg17660833 in KIRC, has been implicated in T cell dysfunction and is frequently upregulated in the tumor microenvironment." (PMID 39716176, 2024). "Based on the previous studies, the upregulated levels of HRH1/HRH2 and tumor-associated MCs may play crucial roles in promoting tumorigenesis and progression of OSCC." (PMID 35587368, 2022). "Next, we assessed whether HRH1 gene polymorphisms were connected to OSCC clinicopathologic features including the primary tumor size, clinical stage, histopathologic grade, and tumor metastatic statuses." (PMID 35587368, 2022). "We also determined whether apigenin suppressed histamine-induced tumor cell proliferation by affecting the expression of the histamine H1 (HRH1) or H3 receptor (HRH3)." (PMID 34568014, 2021). "Regarding therapeutic implications, the combined inhibition of HRH1 and STAT3 enhanced tumor-suppressive effects compared to HRH1 targeting alone in OSCC cells and a xenograft model." (PMID 40113769, 2025). "Consistent with our in vitro findings, IHC staining of HRH1, ADAM9, and vimentin in tumor tissues from SAS-shHRH1-injected mice indicated downregulation of these proteins compared to control mice." (PMID 40113769, 2025). "Activation of the histamine H1-receptor (HRH1) drives oncogenic progression by engaging key survival cascades, including the ERK and NF-κB signaling pathways, which collectively enhance tumor cell growth and confer resistance to programmed cell death." (PMID 41227370, 2025). "Some studies have reported that histamine and histamine receptor H1 (HRH1) induce T cell dysfunction and immunotherapy resistance, promoting tumor growth in mice and humans." (PMID 39839794, 2024). "At the protein level, we observed significantly higher concentrations of HRH1, HRH2, and HRH4 in tumor tissues than those in control tissues (p < 0.05)." (PMID 39267843, 2024). "We found that CHST2 and the well-known target genes of the proposed drugs, HRH1, and EGFR/ERBB2, were co-expressed in the GBM tumours as shown in iNetModels." (PMID 39063109, 2024).
tumor (continued). "IL6high iCAF exhibited a distinct ligand expression involving IL6, which interacted with migratory tumor and M1/M2-like TAMs through IL6R, and HRH1 in endothelial cells to activate the inflammatory response and angiogenesis." (PMID 38892065, 2024). "To evaluate the inhibitory effect of HRH1 on the tumor microenvironment (TME) in PDAC, we investigated the effects of Az, a Food and Drug Administration (FDA) approved HRH1 antagonist, as well as its synergistic effect on αPD-1 treatment." (PMID 38715057, 2024). "In the current study, we found that HRH1 was upregulated in OSCC and was correlated with larger tumor sizes and poor prognoses of OSCC patients, suggesting an oncogenic role of HRH1 in OSCC." (PMID 35587368, 2022). "To further determine the functional role of HRH1 in facilitating the progression of HNSCC, we evaluated the effect of HRH1 expression on cell behaviors, including cell growth and metastasis, two fundamental steps of tumor progression." (PMID 40113769, 2025). "Expression was confirmed at the protein level, and HRH1 expression in tumor cells was higher than that in paired normal ductal cells." (PMID 38715057, 2024). "Moreover, immunohistochemical analysis revealed in the HRH1 knockdown with αPD-1 group (sh2 + αPD-1), an increase in Granzyme B expression and CD8 T cell infiltration compared to other groups was observed within the tumor." (PMID 38715057, 2024). "The addition of HRH1−/− or antihistamine H1-antihistamine fexofenadine (FEXO) eliminated TAM-mediated T cell inhibition by promoting T cell proliferation and upregulating cytotoxic immune cells and cytolytic effector molecules, enhancing the ability to kill tumor cells." (PMID 35378699, 2022). "To investigate the clinical relevance of HRH1 in HNSCC, we initially assessed HRH1 gene expression levels between tumor and noncancerous tissues using three online databases: TIMER2.0, TNMplot, and GEO." (PMID 40113769, 2025). "Results showed that the mRNA levels of HRH1 and HRH3 were not significantly changed by apigenin treatment, indicating that apigenin did not inhibit the histamine-induced increase in tumor cell proliferation by affecting the expression of HRH1 and HRH3." (PMID 34568014, 2021).